NNMT (nicotinamide N-methyltransferase)
Diseases named in the same sentence as NNMT in open-access papers (continued):
Sharing a sentence is not in itself a finding about the gene and the disease.
melanoma (13 papers, 2021 to 2025). A malignant, usually aggressive tumor composed of atypical, neoplastic melanocytes. "The functional role of NNMT was investigated by silencing the enzyme in melanoma cell lines, which, in vitro, was associated with a reduction in melanoma cell proliferation and migration." (PMID 40941017, 2025). "Enzymes such as N-methyltransferase (NNMT) and paraoxonase-2 (PON2) are also being investigated for their diagnostic and prognostic value in melanoma." (PMID 40941017, 2025). "Results obtained in our recent study clearly demonstrated that NNMT knockdown led to a significant reduction of cell proliferation and migration of melanoma cell lines." (PMID 38504052, 2024). "Different studies demonstrated that NNMT is overexpressed in melanoma specimens, including cutaneous and oral melanoma." (PMID 36551302, 2022). "In another study, NNMT activity was analyzed by shRNA-mediated silencing of the enzyme in the melanoma cell lines A375 and WM-115 and it was found that downregulation of NNMT induced a decrease in the proliferation and migration of melanoma cell lines." (PMID 36143291, 2022). "In another study, the functional role of NNMT was investigated through shRNA-mediated silencing of the enzyme in the melanoma cell lines A375 and WM-115." (PMID 34638427, 2021). "The same research group investigated the role of NNMT in 30 samples of primary malignant melanoma, comparing oral malignant melanomas (OMM) and cutaneous melanomas (CM)." (PMID 34827592, 2021). "Additionally, in this review, we highlight markers such as nicotinamide N-methyltransferase and TBC proteins that show promising potential as diagnostic markers in melanoma." (PMID 36143291, 2022). "NNMT is being recognized as a promising treatment target of melanoma." (PMID 36551302, 2022). "Overexpression of NNMT has been reported in a wide range of malignancies, including melanoma." (PMID 36012419, 2022). "Moreover, further work in melanoma cell lines found that NNMT silencing through enzyme knockdown conferred chemosensitivity, highlighting it as a potential molecular target for future chemotherapeutic agents." (PMID 35205743, 2022). "In addition, the knockdown of NNMT expression in melanoma cell lines significantly reduces cell proliferation and migration, and the inhibition of NNMT enzyme activity increases the sensitivity of melanoma cells to dacarbazine treatment." (PMID 36551302, 2022). "The immunohistochemical analysis revealed that NNMT expression was significantly higher in cutaneous malignant melanoma samples, but oral malignant melanoma samples exhibited more strongly stained cells, thus suggesting a potential involvement of NNMT in oral malignant melanoma." (PMID 34638427, 2021). "Moreover, the enzyme downregulation in melanoma cells was associated with an increased sensitivity to treatment with dacarbazine, suggesting that NNMT could be involved in mechanisms promoting melanoma cell resistance to chemotherapy." (PMID 38504052, 2024). "The study of NNMT, PON2, Nrf2, MITF, IDO, and MDM2 as potential biomarkers in melanoma holds great promise for improving diagnosis and advancing targeted therapies." (PMID 37629523, 2023). "However, in melanoma, elevated NNMT expression was related to a better prognosis, which has not been previously documented and may need future investigation." (PMID 36386816, 2022).
lung carcinoma (12 papers, 2014 to 2025). "Increased NNMT expression and activity have been implicated in several types of human cancers, including lung cancer." (PMID 35387964, 2022). "Encouragingly, some studies have identified small-molecule inhibitors of NNMT with anti-cancer effects in lung cancer cells, presenting promising candidates for future preclinical and clinical investigations." (PMID 38809277, 2024). "Knockdown of NNMT in lung cancer cells enhances drug sensitivity by modulating autophagy, providing a promising therapeutic target to overcome chemoresistance in NSCLC." (PMID 39035994, 2024). "It has been shown that bisubstrate NNMT inhibitors significantly lower the concentration of MNA in lung carcinoma cells and endothelial cells." (PMID 38397036, 2024). "Knockdown of NNMT effectively reversed osimertinib resistance in lung cancer, while NNMT knockdown cell lines exhibited increased autophagic flux." (PMID 39035994, 2024). "Most importantly, the natural NNMT inhibitor yuanhuadine can reverse epidermal growth factor receptor tyrosine kinase inhibitor resistance in lung cancer cells." (PMID 35756670, 2022). "In our study, we investigated the correlation between NNMT and other genes in lung cancer." (PMID 39035994, 2024). "In contrast, decreased expression of NNMT was found in bladder, liver, and lung cancers." (PMID 36817086, 2023). "NNMT is expected to be a novel serum tumor marker of lung cancer and colorectal cancer." (PMID 35756670, 2022). "The study hypothesized that NNMT knockdown would enhance drug sensitivity by modifying autophagic processes, providing a potential new therapeutic target for overcoming chemoresistance in lung cancer." (PMID 39035994, 2024). "Proteomic analysis was utilized to identify changes in protein expression following NNMT knockdown in H1975 and H1975 osimertinib resistance (H1975OR) lung cancer cell lines." (PMID 39035994, 2024). "Along these lines, we utilized the natural antitumor compound YD to target AXL degradation which exhibits anti-proliferative activities against various human lung cancer cells by regulating AXL, SerpinB2, NNMT, and BMP422,39–42." (PMID 31043587, 2019).
clear cell renal cell carcinoma (11 papers, 2009 to 2025). "We systematically investigated NNMT expression and its metabolic interactions in clear cell renal cell carcinoma (ccRCC), a prominent RCC subtype with metabolic alterations, to elucidate its role as a drug target." (PMID 35678045, 2022). "A genomic and proteomic examination of 232 cases of renal clear cell carcinoma revealed that NNMT contributes to the immune response of renal cell carcinoma via one-carbon metabolism and is a potential therapeutic target." (PMID 36386816, 2022). "Consistent with this, global H3 methylation on lysine 9 (H3K9) and lysine 27 (H3K27) was decreased in renal clear cell carcinoma cells overexpressing NNMT." (PMID 31294922, 2019). "An increased NNMT expression was found in 100% of clear cell renal cell carcinomas, and NNMT expression levels inversely correlated with tumor size, indicating a possible role of the enzyme in tumor growth." (PMID 23990942, 2013). "Interestingly, the upregulation of NNMT was found to be inversely correlated with tumor size in renal clear cell carcinoma, suggesting that the enzyme may be significant in an initial phase of malignant conversion." (PMID 19216803, 2009). "In clear cell renal cell carcinoma, GPX8 silencing inhibits tumorigenesis by regulating nicotinamide N-methyltransferase (NNMT)." (PMID 38515109, 2024). "In clear cell renal cell carcinoma, GPX8 regulates NNMT expression through the IL6-STAT3 signaling axis and inhibits ccRCC cell survival by blocking this axis through activation of AMPK." (PMID 38515109, 2024). "However, NNMT protein is overexpressed in renal clear cell carcinoma (ccRCC) compared to non-tumor tissue, and high NNMT expression in primary ccRCC has been associated with poor prognosis in an independent cohort." (PMID 40853419, 2025).
fatty liver disease (11 papers, 2018 to 2024). A reversible condition wherein large vacuoles of triglyceride fat accumulate in liver cells via the process of steatosis. "However, another study found that high NNMT expression causes fatty liver disease by modulating the NAD level that, in turn, regulates SIRT3." (PMID 36750850, 2023). "Recent data have suggested that nicotinamide N-methyltransferase (NNMT) is an important contributor to liver steatosis following chronic alcohol consumption." (PMID 37759956, 2023). "The overexpression of NNMT induces hepatic steatosis and fibrosis and decreases liver NAD+ in mice fed a high-fat diet containing NAM, thus contributing to fatty liver disease." (PMID 33609766, 2021). "We focused on molecules such as PLIN2 and NNMT, which were suggested by a proteomic analysis to be responsible for the effect of linagliptin on hepatic steatosis." (PMID 33105604, 2020). "In this study, we investigated the effects of NNMT on hepatic steatosis and fibrosis using transgenic (Tg) mice that overexpress NNMT." (PMID 29872122, 2018). "In conclusion, we demonstrated that NNMT overexpression in mice administered a NAM-supplemented HFD promoted hepatic steatosis and fibrosis." (PMID 29872122, 2018). "When fed a high-fat diet containing NAM, a precursor for NAD+, these NNMT-overexpressing mice exhibited fatty liver deterioration, following increased expression of the genes mediating fatty acid uptake as well as decreased very low-density lipoprotein secretion." (PMID 36837811, 2023). "Similarly, in the setting of alcohol-induced fatty liver development, NNMT inhibition was observed to protect against hepatic steatosis and to be associated with activation of AMPK and suppression of hepatic de-novo lipogenesis." (PMID 36104373, 2022). "Hepatic quantitative proteomic and phosphoproteomic analyses revealed that perilipin-2 (PLIN2), major urinary protein 20 (MUP20), cytochrome P450 2b10 (CYP2B10), and nicotinamide N-methyltransferase (NNMT) are possibly involved in the process of the amelioration of hepatic steatosis by linagliptin." (PMID 33105604, 2020). "Thus, our findings uncovered the potential involvement of NNMT in the pathogenesis of fatty liver and hepatic fibrosis." (PMID 29872122, 2018). "When fed a high fat diet containing NAM, a precursor for nicotinamide adenine dinucleotide (NAD)+, these NNMT-overexpressing mice exhibit fatty liver deterioration following increased expression of the genes mediating fatty acid uptake and decreased very low-density lipoprotein secretion." (PMID 29872122, 2018). "Therefore, targeting NNMT may serve as a therapeutic strategy for treating fatty liver and fibrosis." (PMID 29872122, 2018). "NNMT overexpression, in conjunction with elevated NAM levels, augments hepatic steatosis by inhibiting Sirt3 activity." (PMID 29872122, 2018). "Our data suggested that when NAM, an NMMT substrate, was abundantly available, NNMT activation drove the depletion of both NAD+ and SAM, leading to liver steatosis and fibrosis." (PMID 29872122, 2018). "NNMT overexpression induced the genes important for hepatic steatosis and fibrosis by reducing the tissue NAD+ content and methylation pool, indicating that NNMT links NAD+ and methionine metabolism and contributes to the progression of fatty liver disease." (PMID 29872122, 2018). "However, the details in the mechanism for the involvement of NNMT in hepatic energy metabolism or hepatic steatosis have not been fully resolved." (PMID 29872122, 2018).
neuroblastoma (9 papers, 2013 to 2025). Neuroblastoma (NB) is the most common solid, extracranial childhood tumor. "The induction of NNMT expression in the human neuroblastoma cell line SH-SY5Y led to a significant increase in total glutathione (GSH), free GSH and its oxidized form (GSSG), together with a reduction in the GSH:GSSG ratio, as well as in ROS content." (PMID 41301471, 2025). "We have recently shown that NNMT expression in SH-SY5Y human neuroblastoma cells decreased oxidative stress." (PMID 33387303, 2021). "NNMT stabilizes sirtuin 1 in prostate cancer cells, whereas NNMT increases complex I activity in SH-SY5Y human neuroblastoma cells via sirtuin 3, suggesting a central role of NNMT in regulating energy homeostasis." (PMID 34680237, 2021). "Moreover, increase in NNMT expression and treatment with N1-methylnicotinamide significantly decreased cell death in a human neuroblastoma-derived cell line, suggesting that NNMT expression is involved in maintaining cell viability." (PMID 23990942, 2013).
oral squamous cell carcinoma (9 papers, 2013 to 2026). "NNMT upregulation was already reported in oral squamous cell carcinoma, but its downregulation was associated with increased sensitivity to 5-fluorouracil in esophageal squamous cell carcinoma cells." (PMID 34298834, 2021). "In our previous works, we reported an enhanced expression of NNMT in numerous cancers, such as renal cell carcinoma (ccRCC), oral squamous cell carcinoma (OSCC), bladder urothelial carcinoma, non-small cell lung cancer (NSCLC), and skin malignancies." (PMID 38504052, 2024). "Although previous studies have shown that NNMT is frequently dysregulated to promote the onset and progression of many malignancies, its expression profile, prognostic value and function in oral squamous cell carcinoma (OSCC) are still unknown." (PMID 36291696, 2022).
renal cell carcinoma (9 papers, 2011 to 2024). "Our previous studies have also shown that NNMT is over-expressed in a large proportion of renal cell cancers and that high expression of NNMT is significantly associated with unfavorable prognosis." (PMID 24558488, 2014). "Several studies revealed that NNMT was up-regulated, depending on the stage of progression in renal cell carcinoma, and its expression played a critical role in the invasive potential of human ccRCC cells." (PMID 36118874, 2022). "Xenograft experiments revealed that NNMT overexpression empowered the resistance to radiation therapy in renal cell carcinoma." (PMID 35440542, 2022). "Among urological neoplasms, renal cell carcinoma (RCC) was the first to be examined in regard to potential NNMT involvement, in which enzyme overexpression was described." (PMID 34439880, 2021). "In our previous works, we analysed NNMT expression in renal cell carcinoma (RCC), OSCC, urothelial carcinoma (UC) of the bladder and in non-small cell lung cancer (NSCLC)." (PMID 23990942, 2013). "Therefore, we performed siRNA‐mediated knockdown of NNMT in the 786‐O renal cell carcinoma cell line (NNMTkd) and analysed the cell lysates by LC‐QTOF‐MS." (PMID 35678045, 2022). "Further, we identify NNMT as biomarker for poor prognosis, and verify that NNMT overexpression mediated homocysteine metabolism dysregulation is a potential therapeutic opportunity for renal cell carcinoma." (PMID 35440542, 2022). "Finally, we present a case study of the use of caCORRECT to reliably identify biomarkers for renal cell carcinoma, yielding two diagnostic biomarkers with potential clinical utility, PRKAB1 and NNMT." (PMID 21957981, 2011).
renal carcinoma (8 papers, 2009 to 2025). A carcinoma arising from the epithelium of the renal parenchyma or the renal pelvis. "In addition to CRC, abnormal expression of NNMT was also reported in other tumors such as papillary thyroid cancer, glioblastoma, gastric cancer, renal carcinoma, oral squamous cell carcinoma, lung cancer, pancreatic cancer and ovarian clear cell carcinoma." (PMID 24558488, 2014). "NNMT, PLOD2, HAPLN3, PLIN2, and SLC16A3 showed medium to strong tumor-specific staining in more than 90% renal cancer samples, indicating higher general applicability of these biomarkers." (PMID 35440542, 2022). "We observed increased protein lysine-homocysteinylation (K-Hcy) levels in NNMT-overexpressing and SAH-supplemented cultured renal cancer-derived ACHN, 786-O, 769-P, and A-498 cells." (PMID 35440542, 2022). "NNMT overexpression reduced DNA damage in stressed ACHN, 786-O, and 769-P cells as evidenced by the levels of γ-H2AX detected using immunofluorescence staining and western blotting and by DNA damage detection using the comet assay, in cultured renal cancer cell lines." (PMID 35440542, 2022).
renal fibrosis (8 papers, 2022 to 2025). A final common manifestation of a wide variety of chronic kidney diseases characterized by glomerulosclerosis and tubulointerstitial fibrosis. "Disruptions in methionine metabolism have been linked to increased nicotinamide N-methyltransferase (NNMT) expression in the kidneys, a marker associated with renal fibrosis." (PMID 40243426, 2025). "The upregulation of NNMT expression in the kidneys has been linked to disturbances in methionine metabolism and consequent renal fibrosis." (PMID 38354117, 2024). "Since the renal NNMT expression was increased in the renal fibrosis model, to determine the causal relationship between NNMT and renal fibrosis, we created an NNMT-deficient (NNMT-KO) mice." (PMID 35430611, 2022). "However, this study clearly showed that NNMT deficiency and overexpression resulted in lower and higher renal fibrosis respectively, suggesting that NNMT contributed to the worsening of inflammation and fibrosis." (PMID 35430611, 2022). "In other words, alleviation of renal fibrosis due to NNMT deficiency might be mediated through the elevation of renal NAD + and SAM/SAH ratio." (PMID 35430611, 2022). "To investigate the relationship between NNMT expression and renal fibrosis, we compared the area of fibrosis between the high and low NNMT expression groups (high group, n = 10; low group, n = 9) and found that high NNMT expression was significantly associated with the high degree of renal fibrosis." (PMID 35430611, 2022). "As a protective role, Nicotinamide N-methyltransferase (NNMT) can reduce oxidative stress and cell death of PT induced by lipotoxicity, and NNMT can also improve renal fibrosis by targeting the TGF-β1 signalling pathway." (PMID 38270638, 2024). "We initially investigated renal fibrosis and NNMT expression in the kidneys of mice subjected to UUO for 3, 7, 10, and 14 days." (PMID 37953778, 2023). "Either NNMT over-expression or MNA gavage administration ameliorated renal fibrosis, possibly as a result of transforming growth factor (TGF)-β inhibition." (PMID 37814337, 2023). "We propose that NNMT promotes fibroblast activation and renal fibrosis, making NNMT a novel target for preventing and treating renal fibrosis." (PMID 37953778, 2023). "Both in vivo and in vitro findings revealed that NNMT expression was positively correlated with the degree of renal fibrosis." (PMID 37953778, 2023). "To determine the changes in NAD + metabolites and NNMT expression in renal fibrosis, we used the mouse UUO model." (PMID 35430611, 2022). "Further investigation is needed to elucidate the regulation of NNMT expression and its effects, primarily on renal fibrosis." (PMID 35430611, 2022). "We also conducted two clinical studies to investigate the alteration of NAD + metabolites in human CKD and the role of NNMT in human renal fibrosis." (PMID 35430611, 2022). "This study investigated the pathological significance of NAD + metabolites and NNMT in renal fibrosis using NNMT knockout mice." (PMID 35430611, 2022). "To investigate the expression of NNMT and its relationship with renal fibrosis in human kidney tissue, we used human renal biopsy samples." (PMID 35430611, 2022). "However, an increase in NNMT expression and methylated catabolites of nicotinamide has also been reported to contribute to renal fibrosis and fatty liver in other experimental models." (PMID 39354697, 2024). "Our findings suggest that targeting NNMT as an useful control strategy for progressive renal fibrosis could be beneficial." (PMID 37953778, 2023). "Furthermore, NNMT knockout mice that developed renal fibrosis showed a decrease in renal NNMT expression and NAD+ salvage pathway metabolites such as NAM, NMN, and NAD+, as well as an increase in degradation products of NAM such as MNA, N-Me-2PY, and N-Me-4PY." (PMID 36613582, 2022). "Moreover, NNMT depletion improved renal fibrosis, and renal NAD + increased at an early stage of UUO." (PMID 35430611, 2022).